AKT1 (AKT serine/threonine kinase 1)
Diseases named in the same sentence as AKT1 in open-access papers (continued):
Sharing a sentence is not in itself a finding about the gene and the disease.
tumor (continued). "In the cases of invasive BC from the TCGA database in UALCAN, the mRNA levels of AKT1, ESR1, HSP90AA1, CASP3, SRC, and MDM2 were significantly increased in tumor tissues." (PMID 36882618, 2023). "Mechanically, the activated AKT1 phosphorylates and inhibits SOD2 in mitochondria, thereby promoting mitochondrial ROS accumulation and subsequent cell death in confined tumor cells." (PMID 37296072, 2023). "Members of the AKT family include three isoforms, AKT1, AKT2, and AKT3, which are involved in different mechanisms of tumor progression." (PMID 36927770, 2023). "We found that the oncogene PDIA3P1, and tumor-suppressor RRN3P3, promote the RNA and protein expression of their targeted immune-involved genes AKT1 and EZH2 via miR-34a-5p and miR-26b-5p, respectively." (PMID 36438489, 2022). "The circPSMA1/miR-637/AKT1 axis in TNBC enhances the proliferation and migration ability of TNBC cell lines and promotes tumor metastasis in BALB/c mice." (PMID 36175921, 2022). "The top 3 hub-genes, namely AKT1, ESR1 and HSP90AA1, identified by protein–protein interaction network analysis using Tamarixetin targets, are known to play prominent roles in tumor progression." (PMID 35273218, 2022). "In our previous study using tissue microarray data from the WCHS participants, phosphoprotein expression of MTOR, AKT1, and S6K1 were consistently lower in patients with a higher grade tumor, larger tumor, more advanced disease, or TNBC." (PMID 35608730, 2022). "The western blotting assays of tumor tissue lysates showed that OSW-1 inhibited the expression levels of p-PI3K and p-Akt1 in the OSW-1 treatment group compared to the control group." (PMID 36133816, 2022). "The relative expressions of AKT1, MMP2, and MMP9 genes were higher in tumour tissues than in non‐neoplastic liver tissues." (PMID 35811356, 2022). "Clear answers will require large phase 3 studies, and results from the CAPItello-291 trial in which NGS is used to identify PIK3CA, AKT1, and PTEN tumour alterations are eagerly awaited." (PMID 35671774, 2022). "Simultaneous injection of myr-AKT1, TAZS89A, and shLuc resulted in a high tumor burden, and AKT-shLuc-TAZ mice required sacrifice between 12 and 14 weeks post-injection." (PMID 35655220, 2022). "More importantly, we further demonstrated that TRIB3 interacted with AKT1 to up-regulate FOXO1 and SOX2 expression, which was indispensable for the pro-tumor effects induced by integrin αvβ3." (PMID 35473511, 2022). "Spatial profiling did not further illuminate the mechanism of recurrence, since ROIs contained expression of tumor cell marker NY-ESO-1 with other oncogenic pathway markers (eg, PTEN, AKT1, and CCND1) as well as immune lineage and T-cell exhaustion markers." (PMID 35264439, 2022). "We experimentally validate the oncogene PDIA3P1, and tumor-suppressor RRN3P3, which promote the RNA and protein expression of their targeted immune-involved genes AKT1 and EZH2 via miR-34a-5p and miR-26b-5p, respectively." (PMID 36438489, 2022). "On the other hand, Gepia database revealed that in CC tumor tissues, RSF-1 expression is positively correlated with VEGFA, AKT1 and GSK3β expression." (PMID 36056431, 2022). "Previous studies have shown that activated Akt1 stimulates NHEJ repair, which then contributes to chemo- or radio-resistance in some tumor cells." (PMID 35563814, 2022). "Overall, our data suggest that deregulated Akt1/mTOR signaling in ERMS cells, promoting an aggressive tumor phenotype, can become the Achilles’ heel for the tumor if the availability of some nutrients or their metabolism is disrupted." (PMID 36139434, 2022). "The chemotherapeutic resistance-related genes (mainly AKT1 and ERBB1) and EGFR tyrosine kinase inhibitor-related genes were decreased in the effective group, and multiple tumor driver genes (mainly Myc) were increased in the ineffective group." (PMID 36230574, 2022).
tumor (continued). "AKT isotypes, such as AKT1, AKT2 and AKT3, have been suggested as therapeutic targets for angiogenesis-related abnormalities such as tumor or ischemic injury." (PMID 36286049, 2022). "The analysis revealed that the relative expressions of AKT1, MMP2, and MMP9 genes were increased in HCC tumour tissues (n = 373) compared with the normal samples (n = 50)." (PMID 35811356, 2022). "We found that a subset of genes, for instance activated Braf and Akt1, did accelerate KRAS KO tumor formation in nude mice." (PMID 33674596, 2021). "The link between EGFR and DSB repair suggests strategies to modulate tumor radiosensitivity by inhibiting NHEJ indirectly with available drugs that target EGFR and AKT1/3 pathways." (PMID 34337349, 2021). "In vitro, circNRIP1 can be transmitted between GC cells via exosome communication to further regulate AKT1 expression and EMT by targeting miR-149-5p, thereby promoting the proliferation, migration, and invasion of GC cells and tumor metastasis in vivo." (PMID 34195097, 2021). "The treated tumor showed several CNVs in driver genes, including amplifications in MCL1, TERT, CCND1, AKT1, MYC, EGFR, and FGFR3; deletions in CDK1B, CDKN2A and CDKN2B; a PIK3CA hotspot mutation; and a high TMB." (PMID 34680239, 2021). "mTOR is a downstream molecule of AKT1, and the AKT/mTOR pathway is one of the classical signaling pathways mediating tumor metabolic homeostasis." (PMID 33718157, 2021). "In prostate cancer, studies show that tumor genomic alterations, including copy number variations of genes frequently altered in metastatic PCa (i.e., MYC, AKT1, PTK2, KLF10, and PTEN), are represented in large EVs." (PMID 33805398, 2021). "In our study, the HSP90AA1 knockdown inhibited the AKT1 and ERK pathways, which were over-activated in tumor tissues." (PMID 35095481, 2021). "Furthermore, a metabolic balance exists in tumor cells, as exemplified by how heightened ROS levels may confer survival and growth advantages in high AKT1 tumor cells, but also makes cells vulnerable to oxidative stress beyond a certain threshold which then inhibits growth." (PMID 34831420, 2021). "It was found that the upstream molecules PHLPP2 and PTEN of Akt1 affect its phosphorylation process, which in turn affects the PI3K/Akt signaling pathway, and exerts an anti-tumor effect." (PMID 33692692, 2021). "Based on our collected kidney normal and RCC samples, we compared the expression of AKT1 (AKT), AKT2 and AKT3 in RCC tumor tissues versus normal tissues." (PMID 34384473, 2021). "Our findings suggest that many of patients who had elevated expression of tumor‐specific signatures such as ESR1, AR, VEGF, AKT1/2/3, CCND1, CDK1, and MMP9 had significantly poorer disease‐free survivals compared with the remaining subgroups." (PMID 33275817, 2021). "In normal cells, PTEN, a tumor suppressor, dephosphorylates the phospholipid PIP3 and inhibits the AKT1 signaling pathway." (PMID 34831420, 2021). "Downregulation of LINC01419 suppresses tumor growth and promotes autophagy through inactivation of the PI3K/Akt1/mTOR pathway in GC." (PMID 34805143, 2021). "Paired tumor sections from both pre-treatment and post-treatment showed that there was significant upregulation of the PI3KCA, AKT1, and mTOR genes and their corresponding protein levels." (PMID 35582035, 2021). "The interaction of AKT1, AKT3, and DNA-PKcs promote tumor-cell proliferation and survival after irradiation." (PMID 34665844, 2021). "The downregulation of LINC01419 suppresses tumor growth and promotes autophagy through the inactivation of the PI3K/Akt1/mTOR pathway in GC (Wang L.-L." (PMID 34805143, 2021).
tumor (continued). "PI3Ks are a family of related intracellular signal transducer enzymes that are activated by the stimulation of RTKs and/or activation of RAS family proteins, while AKT1, a Ser/Thr protein kinase, mediates the PI3K effects on tumor growth and progression." (PMID 34205978, 2021). "Copy number gain of PIK3CA was present in all three PDX models, as well as AKT1 in TC1 and TC4 PDX tumours." (PMID 33144587, 2020). "Regarding the contradicting data on the role of AKT1 in the invasion of tumor cells and the poor knowledge of signaling around ARHGAP29 and AKT1, possible crosstalk between ARHGAP29 and AKT1 signaling should be investigated in detail." (PMID 33291460, 2020). "Down-regulation of PI3K, AKT1 and PI3K/mTOR reduced the self-renewal and survival of BCSCs in vitro and their tumor initiation and self-renewal ability in vivo." (PMID 33584277, 2020). "GAB2 performs all these various oncogenic functions by mediating PI3K/AKT1/mTOR, MAPK, and IKKβ pathways in tumor cells that harbor GAB2 alteration." (PMID 33488950, 2020). "MiR-199a suppresses tumor growth and ameliorates chemoresistance via targeting K-RAS via protein kinase B α (namely AKT1) and extracellular-regulated protein kinases (ERK) pathways." (PMID 32677950, 2020). "At the same time, the presence of cell migration inhibitors (APOE, AKT1, BARD1, GDF2) in exosomes from blood HFs accompanied by low stimulating effects on the migration velocity of tumor cells." (PMID 32218180, 2020). "Further, the gene expression profiling of the tumour exhibited a higher level of EPCAM, CK20, KRAS, AKT1, BRAF and CD133 expression, while lower levels of expression were observed in NANOG, MMP9 and APC genes." (PMID 33092235, 2020). "In the current study, we analyzed the newly identified direct phosphorylation-dependent binding of LASP1 to AKT1 and CXCR4, two major players in tumor progression." (PMID 32075106, 2020). "Knock down of S100A9 diminished tumor proliferation and invasion through the inhibition of MAPK, NF-kappa B and AKT1." (PMID 33203795, 2020). "Two proven key signaling pathways related to tumor progression and chemotherapy resistance, the phosphatidylinositol 3-kinase (PI3K)-AKT serine/threonine kinase 1 (AKT1) and transforming growth factor β1 pathways, were also significantly enriched in our study." (PMID 33365318, 2020). "Increasing evidence has demonstrated that constitutive activation of AKT1 induced epithelial-mesenchymal transition (EMT), which is an essential step in tumor invasion." (PMID 33203795, 2020). "Increased expression of RSK1p90 phospho-S380 (p = 0.010), Akt1 phospho-S473 (p = 0.026) and ERK1/2 phospho-Y204/197 (p = 0.015) in tumor ccRCC compared to respective non-tumor tissue has been shown." (PMID 31861116, 2019). "This is the case of the amplified oncogenes AKT1 and WT1, and of the receptor tyrosine kinase gene FLT4, which regulates lymphangiogenesis and tumor metastasization to lymphatic vessels." (PMID 31616467, 2019). "However, none of the tumor samples in our cohort had Akt1 mutations or amplifications." (PMID 31227862, 2019). "It has been reported that mTOR acts as downstream molecule of AKT1, and the AKT/mTOR pathway is one of the classic signalling pathways to mediate tumour metabolic homeostasis, which is beneficial for tumour growth and metastasis." (PMID 30717751, 2019). "AKT1 knockdown has an anti-tumor effect, whereas AKT2 ablation can promote tumor growth and AKT3 ablation has little effect." (PMID 31454965, 2019).
tumor (continued). "The current study open news avenues to further dissect the potential driving mechanisms and functional consequences of the reduced levels of AKT1, ERK1/2, NPAS4 and BDNF in tumor brain, especially within the concept of aging." (PMID 29556248, 2018). "We indeed observed a large amount of suppressive macrophages infiltrating in the Akt1/N-Ras-induced HCC tissue and impairment of CTL responses against the tumor." (PMID 30526672, 2018). "Twist1 activity is regulated by the protein kinase Akt1, a member of the highly conserved Akt/PKB serine-threonine kinase family, known to promote tumor initiation and progression." (PMID 30463358, 2018). "EIF3I can specifically upregulated and interact with phospho-Akt1 (Ser473) to prevent de-phosphorylation by phosphatase PP2A and to sustain oncogenic p-Akt1 activity to facilitate tumor progression." (PMID 29568350, 2018). "The observed concomitant downregulation of AKT1, ERK1/2, NPAS4, BDNF, and other NPAS4 targets strongly suggests the importance of these pathways in tumor brain, as it manifests in the hippocampus." (PMID 29556248, 2018). "Indeed, our previous experiments had already shown that the individual distribution of AKT kinases and SGK-1 differ between individual tissues, which might explain why shc-1;akt-1 germline tumor are potently suppressed by RNAi down-regulation of either akt-2 or sgk-1." (PMID 28549065, 2017). "Strikingly, down-regulation of akt-2 or sgk-1, like daf-2, suppressed germline hyperplasia in shc-1;akt-1 animals, indicating that the activity of DAF-2, AKT-2 or SGK-1 in this context contributed to germline tumor formation." (PMID 28549065, 2017). "The mRNA expression of Akt1 was detectable in all PDAC cells by qRT-PCR, as well as in the originator tissues of the primary tumor cell cultures." (PMID 28061880, 2017). "Here we describe the mechanisms by which AKT1 and AKT2 play specific roles in tumor growth and dissemination in IBH-6 and T47D human cell lines." (PMID 28287129, 2017). "Phosphorylation of the extreme C-terminal region (Ser477/Thr479) of AKT1 by CDK2/Cyclin A2 complex primes and promotes AKT1 Ser473 phosphorylation, resulting in increased AKT-driven tumour growth in vivo." (PMID 28082369, 2017). "Meanwhile, transfection of cells with constitutively active Akt1 greatly blocked the inhibitory effect of ATR-1 as well as the up-regulation of Bax and Bad, thereby proving that the anti-tumor effect of ATR-1 relies on the inhibition of PI3K/Akt/mTOR pathway." (PMID 26931119, 2016). "Increased AKT1 (induced by overexpression of FHL2) would in turn promotes the activation of NFκB and AP-1, forming a positive-feedback loop to drive GCT tumor malignant progression." (PMID 27415427, 2016). "It is therefore likely that in tumours displaying activated PI3K signalling, both Akt1/2 and SGK1/SGK2 would be elevated and stimulate proliferation by phosphorylating an overlapping subset of substrates." (PMID 27481935, 2016). "When ERβ is activated by the selective agonist KB9520, SIRT1 and FOXM1 are down regulated, resulting in increased acetylated AKT1 and interaction with PARP1, HSC70 and GADPH in tumor cells, both in vitro and in vivo." (PMID 26885609, 2016). "Here we report that the PI3K/Akt1/IL-6/STAT3 signalling pathway regulates generation and stem cell-like properties of Non-Small Cell Lung Cancer (NSCLC) tumor initiating cells (TICs)." (PMID 26486080, 2015). "Our data show that both Akt1 and Akt2 are expressed in ATII cells, the putative tumor initiating cells, but that Akt1 is expressed at a higher level in these cells." (PMID 24722238, 2014).
tumor (continued). "Western blots showed expression of Akt1, p-Akt1 (pT308, pS473), PTEN, and EGFR in the tumor tissue homogenates." (PMID 25389442, 2014). "Furthermore, knockdown of AKT1 expression abolished effects of miR-149 overexpression in HepG2 cells, including inhibiting cell proliferation, invasion and migration, indicating that the tumor suppressive roles of miR-149 in HCC were partially mediated by targeting AKT1-mTOR pathway." (PMID 25424347, 2014). "Note that Akt1 is more highly expressed in ATII cells, which are the putative tumor originating cells, whereas Akt1 and Akt2 are expressed at near equivalent levels in Clara cells, which are not susceptible to transformation." (PMID 24722238, 2014). "Based on the immunoreactivity it was apparent that the cell signalling proteins AKT1 and ERK1/2 shuffled from the nucleus to the cytoplasm with tumour progression." (PMID 25167778, 2014). "Akt1 reportedly induces the expression of CXCR4 in PTEN-null PCa cells, and overexpression of Akt-1 promoted intra-tibial tumor growth of PCa cells." (PMID 25566502, 2014). "Moreover, loss of Akt1 or Akt2 did not alter tumor histology or cytokeratin expression." (PMID 23919516, 2013). "Feeding D-PDMP markedly reduced tumor volume by way of decreasing the enzymatic activity of LCS, LCS mass, and consequently LacCer mass, and the angiogenic proteins such as p-AKT-1 and mTOR." (PMID 23671696, 2013). "It is well known that the activation of AKT-1 is dependent on the activation of PI3K and is also kept under control by PTEN tumor suppressor." (PMID 23870437, 2013). "Akt1-induced CXCR4 expression is active in CXCL12-induced cellular invasion, tumor growth, and intraosseous tumor growth in murine model systems." (PMID 23902739, 2013). "All three proteins positively correlated with tumour grade (HER3, p = 0.0029; HER4, p = 0.0118; Akt1, p = 0.0001)." (PMID 21407808, 2011). "Immunoblotting with an anti-ErbB2 antibody demonstrated that the level of ErbB2 protein was dramatically increased in tumours of both origins compared with normal mammary tissue from the same mouse, from FVB mice or from myr-Akt1 transgenic mice." (PMID 18700973, 2008). "The expression of the transgenes was examined at the protein level in tumours (T) and normal mammary gland control (N) taken from tumour-bearing mice of both the MMTV-c-ErbB2 and MMTV-c-ErbB2, MMTV-myr-Akt1 genotypes." (PMID 18700973, 2008). "AKT1 (protein kinase B1), an essential downstream component of the PI3K/Akt signaling pathway, promotes cell growth and inhibits programmed cell death in OS, leading to tumor development and resistance to treatment." (PMID 41158757, 2026). "Finally, alterations in the AKT1 gene, a serine–threonine kinase within the PI3K signaling pathway, promote tumor growth and inhibit apoptosis through unregulated activation." (PMID 40214484, 2025). "High expression of AKT1 mRNA was also observed in tumor tissue specimens, although no statistical difference was detected between the adjacent and cancerous tissues, possibly due to the relatively small sample size in the analysis." (PMID 40599236, 2025). "Furthermore, ART exhibited strong interactions with AKT1, a key molecule in the PI3K/AKT/mTOR signaling pathway, which was widely activated in various malignancies and promotes tumor cell survival and invasive behaviors." (PMID 40303931, 2025). "We observed a reduction in tumor size in the group of mice receiving Akt2-OE CTLs, but no significant change was seen in the groups receiving control or Akt1-OE CTLs." (PMID 40139836, 2025). "For example, AKT1 participated in seven biological processes, EGFR and STAT3 were involved in six, and SRC contributed to five biological processes, highlighting their essential roles in mediating the anti-tumor effects of steamed PJR." (PMID 41465428, 2025).